VIM (vimentin)
Diseases named in the same sentence as VIM in open-access papers (continued):
Sharing a sentence is not in itself a finding about the gene and the disease.
tumor (continued). "Our findings indicated that early-stage OSCC tissues exhibit higher E-cadherin and Smad4 expression, along with lower N-cadherin and Vimentin levels, suggesting their utility as early indicators of tumor progression." (PMID 40507242, 2025). "Immunostains showed that tumor cells were positive for vimentin and MUM1, and scattered tumor cells were positive for CD138 and CD163." (PMID 40161372, 2025). "Immunohistochemically, the tumor cells are typically positive for vimentin, desmin, smooth muscle actin (SMA), and estrogen and progesterone receptors (ER/PR), indicating hormone sensitivity." (PMID 41480427, 2025). "IHC staining of mouse lungs revealed upregulation of MSI2, vimentin, and N-cadherin and downregulation of E-cadherin in the Scr-treated clone #1 tumor-bearing group, whereas these changes were reversed when MSI2 was silenced." (PMID 39990676, 2025). "Recent research reports indicate that VIM protein can influence immune cells infiltration in the tumor microenvironment (Dutsch-Wicherek, Lazar & Tomaszewska, 2011)." (PMID 40256740, 2025). "Previous studies have demonstrated that E3 ubiquitin ligases can regulate Vimentin stability and thereby influence tumor invasion." (PMID 40521243, 2025). "In tumor cells, decreased lncPTEN1 expression leads to Vimentin accumulation, thereby promoting tumor cell metastasis." (PMID 40521243, 2025). "We found that the expression of α-SMA, FAP and Vimentin were significantly elevated in the tumor tissues mixed with stromal cells." (PMID 40703348, 2025). "A band at 57 kDa, consistent with Vimentin, was also observed in samples from patients with both tumor types, although with variable intensity among samples." (PMID 40806708, 2025). "Clinical validation in TNBC specimens reveals that aDMA‐VIMR64 (vimentin R64 aDMA) levels correlate with advanced tumor stages and poor patient prognosis, establishing this modification as a potential prognostic biomarker." (PMID 40884268, 2025). "Patients in the population of a pT3 tumor stage show significantly higher Vimentin expression (p = 0.0152, +/−SEM 0.2%)." (PMID 40523922, 2025). "Our findings that Vimentin expression tracks with tumor invasiveness and metastatic spread demonstrate its role in epithelial–mesenchymal transition (EMT), a critical process in cancer progression." (PMID 40831933, 2025). "CK, Vimentin and Ki-67 (>75%) were positive in the tumor cells, whereas SMARCA4, CD20, LCA, CD3, HMB-45, Melan-A, Epstein-Barr virus (EBV) were negative." (PMID 41170461, 2025). "ZEB1 deficiency prevents P.g.-induced vimentin and MMP-9 upregulation, reducing tumor cell migration, indicating its crucial role in EMT." (PMID 40924302, 2025). "In accordance with myofibroblastic differentiation of the tumor, positive staining for smooth muscle actin, desmin, vimentin, and CD34 is typically observed." (PMID 40797454, 2025). "Western blot analysis of tumor tissues revealed increased E-cadherin expression, decreased vimentin expression, and reduced levels of the PCNA, indicating that G1 can modulate cell phenotype and suppress cell proliferation." (PMID 40867252, 2025). "In the tumor retention model, both bioluminescence imaging and immunohistochemical staining for Ki67, PD-L1 and vimentin showed that CTC clusters were more efficiently retained in lung tissues than single cells." (PMID 41381723, 2025). "In cancer, vimentin is widely acknowledged as the intermediate filament that is a mesenchymal marker promoting tumour cell migration, invasion, and metastasis in multiple cancer types." (PMID 40282554, 2025). "Next, to explore the proliferation and metastasis of cancer cells in BC‐bearing mice, we also immunostained tumor tissues with the proliferation marker Ki67 and the epithelial‐mesenchymal transition markers E‐Cadherin and Vimentin." (PMID 39755930, 2025).
tumor (continued). "Immunohistochemical analysis of the tumor cells showed strong immunoreactivity for vimentin (++), CD31 (++), and ERG (++), with most tumor cells also positive for CD68 (++)." (PMID 40283372, 2025). "This molecular pathway reveals a novel mechanism by which lncPTEN1 functions as a suppressor of tumor metastasis through regulation of the TRIM16-Vimentin axis." (PMID 40521243, 2025). "A series of coronal sections of the entire spinal cord, cervical, thoracic and lumbar of xenograft mouse was examined for cytology (H&E staining), and presence of MB tumour cells was confirmed by staining for expression of human vimentin." (PMID 40664675, 2025). "Polybromo 1 (PBRM1) is a tumor suppressor that controls tumor grade and metastasis of pancreatic ductal adenocarcinoma by regulating vimentin expression." (PMID 40454484, 2025). "In tumor pathology, vimentin is widely recognized as a marker of epithelial-to-mesenchymal transition (EMT), a process associated with tumor progression, increased invasiveness, and therapy resistance." (PMID 40937216, 2025). "Subsequently, immunofluorescence assay was performed to detect the protein expression of EMT markers E-Cadherin and Vimentin in tumor tissues." (PMID 40247422, 2025). "Immunohistochemical profile of tumor cells in our patient showed vimentin, CD68, and alpha-SMA positivity." (PMID 40283372, 2025). "A promising target that has recently gained attention in the context of immunotherapy is extracellular vimentin (eVim), which is secreted by tumour endothelial cells in the majority of solid tumours." (PMID 41009669, 2025). "Immunohistochemically, the tumor exhibits diffuse vimentin positivity and a high Ki-67 proliferative index, consistent with a mesenchymal origin and active mitosis." (PMID 40917595, 2025). "During the EMT process, tumor cells lose epithelial markers like EpCAM and acquire mesenchymal markers such as vimentin driven by transcription factors like Snail and Twist." (PMID 40260304, 2025). "Subsequently, the gain of expression of mesenchymal marker vimentin in tumor cells revealed the induction of EMT in the sgP19/kRAS model, and it is induced by activating the TGFβ/ZEB1 signaling pathway." (PMID 41354626, 2025). "The results revealed that NaHS significantly decreased the expression of Ki67, E‐Cadherin, and Vimentin in tumor tissues obtained from BC‐bearing mice compared to the NC groups, but these effects were abrogated by clodronate liposomes." (PMID 39755930, 2025). "Tumor cells were stained with anti-human vimentin (green), vasculature with CD31 (red), and nuclei with DAPI (blue)." (PMID 41174561, 2025). "EMT-related epithelial cells, characterized by the expression of genes such as FN1 and VIM, showed activation of pathways that regulate cell adhesion, wound healing, and cell growth, suggesting their potential role in tumor invasion and metastasis." (PMID 40520021, 2025). "The strong positive expression of MUC4 and Vimentin, along with the elevated Ki67 index, was indicative of high tumor reactivity." (PMID 40144208, 2025). "Subsequently, we systematically assessed R64‐methylated vimentin levels in clinical TNBC specimens using tumor tissue microarray (TMA) technology." (PMID 40884268, 2025). "Corresponding with the downregulation of circ_0079226, an increase in E-cadherin protein level and a reduction in FOXK1, N-cadherin, and vimentin levels were observed in the tumor tissues." (PMID 39981141, 2025). "By identifying markers linked to tumor aggressiveness, such as TFE3 and Vimentin, clinicians can tailor monitoring and therapeutic interventions, optimizing outcomes for patients with this rare RCC subtype." (PMID 39851801, 2025). "Strong and diffuse immunopositivity for vimentin in correlation with the histology confirmed the mesenchymal cell origin of the present tumour." (PMID 40735304, 2025).
tumor (continued). "High-risk MVI (M2) is often associated with activation of epithelial-mesenchymal transition (EMT), involving downregulation of E-cadherin and upregulation of N-cadherin and vimentin, which enhances tumor cell migration and invasiveness." (PMID 41211437, 2025). "We found that it significantly delayed metastatic progression by suppressing tumor proliferation in primary tumor tissue while exhibiting increased E-cadherin and decreased vimentin expression." (PMID 40867252, 2025). "The results indicated that Ki-67, N-cadherin, and Vimentin expression levels in HB tumor tissues were enormously lower when NAT10 was knocked down, indicating a marked reduction in the proliferation and invasion capabilities of HB cells." (PMID 40303290, 2025). "Vimentin is also involved in many functions outside of cells, for example, marking circulating tumor cells and promoting neural repair." (PMID 41463435, 2025). "In cancer, Vimentin is closely associated with epithelial-to-mesenchymal transition (EMT), a process that enhances tumor invasiveness and metastasis." (PMID 41029537, 2025). "Previous studies on vimentin have mainly focused on cancer, vimentin expression can over‐promote EMT and participate in the adhesion migration invasion of tumor cells and their associated endothelial cells and macrophages." (PMID 39753767, 2025). "These cytokines activate signaling pathways such as SMAD, STAT3, and NF-κB in tumor cells, leading to the downregulation of epithelial markers like E-cadherin and the upregulation of mesenchymal markers such as vimentin and N-cadherin." (PMID 39983469, 2025). "Later, the intercalated duct cell origin was reported because tumor cells co-expressed cytokeratin, vimentin, and desmin." (PMID 41322839, 2025). "Vimentin has been proposed as a potential therapeutic target, and drugs that inhibit vimentin, such as withaferin a and simvastatin, have shown promising results in reducing viral entry and tumor progression." (PMID 39997396, 2025). "Vimentin has been found to drive tumour cell invasion by cross-linking to the F-actin forming the invadopodia through plectin, thus stabilising their formation." (PMID 40282554, 2025). "Multiplex IF analysis was carried out on 95 pre‐NAC BC samples to assess E‐cadherin and vimentin protein expression levels and to determine the percentage of positive cells in the tumor area as well as the staining index of each protein." (PMID 39912409, 2025). "Early FDIM was associated with the upregulation of XIAP (X-linked inhibitor of apoptosis protein) and VIM (vimentin) suggesting an increased epithelial-mesenchymal transition (EMT) and apoptosis resistance during tumour initiation." (PMID 40683913, 2025). "VIM, a cytoskeletal protein linked to epithelial-to-mesenchymal transition (EMT) and tumor progression, was also overexpressed in LSCC samples." (PMID 40149643, 2025). "Western blot analysis further demonstrated elevated E-cadherin expression and reduced levels of N-cadherin, vimentin, and slug in tumor tissues from the LINC00892-overexpressing group compared to the control group." (PMID 40308809, 2025). "The organoids utilized in this study showed expression of TME markers α-SMA and vimentin in patterns similar to in vivo tissues, indicating that key components of tumor-stromal interaction and heterogeneity are also present in tumor organoids." (PMID 41035875, 2025). "In a typical TNBC tumor, the probability for co-expression of AnxA6 and vimentin is higher than with Ki67 or between AnxA6 and Ki67 and supports the use of vimentin and AnxA6 as bona fide markers of invasiveness." (PMID 41279138, 2025). "qRT‐PCR further validated the decreased expression of E‐cadherin, N‐cadherin, and vimentin proteins after MCPIP1 overexpression in tumor cells." (PMID 40874680, 2025).
tumor (continued). "Our findings that detection of Ki67 and AnxA6 together with EpCAM for epithelial/proliferative cells and vimentin for mesenchymal-like/invasive cells can be used to identify these cell types in a typical TNBC tumor for rational treatment strategies." (PMID 41279138, 2025). "VIM, a hallmark of EMT, was overexpressed in LSCC tissues, reinforcing its established role in tumor invasiveness and metastasis." (PMID 40149643, 2025). "Vimentin translocation to the surface of tumor cells, particularly in circulating tumor elements, has been associated with high metastatic capacity." (PMID 41155410, 2025). "The highest expression of vimentin was observed in tumor #9, which had the highest CIN score among these tumors, and partial vimentin expression was observed in tumors with moderate CIN, including tumors #20 and #34." (PMID 40136696, 2025). "Tumor cells in TB and PDCs of CRLMs showed vimentin expression immunohistochemically, suggesting EMT activation, which enhances metastases." (PMID 40629930, 2025). "IHC staining further confirmed tumor's smooth muscle and mesenchymal origins, with positive for vimentin, smooth muscle antibody (SMA), synapsin (Syn), actin, desmin, CD34 (vascular), while negative for and chromogranin A (CgA)." (PMID 39776317, 2025). "Collectively, our findings demonstrate that vimentin R64 aDMA is essential for cell migration under both normoxia and hypoxia, and experimental metastatic progression, highlighting its central role in tumor cell dissemination." (PMID 40884268, 2025). "Overall, these data together suggests vimentin-targeted pritumumab is suitable for further development as an anti-tumor therapeutic." (PMID 40051499, 2025). "The increase in malignant characteristics of C328S cells implies that the original cysteine residue in vimentin acts as a tumour suppressor." (PMID 40690373, 2025). "CK5 and vimentin were strongly expressed in tumor cells within the PDX#1, #2, and #3 tumor tissues, while EGFR was highly expressed in PDX#1 and #2 tumor tissues, but not in PDX#3, consistent with IHC results from patient tissues." (PMID 40551232, 2025). "Among the phosphorylated residues detected, vimentin showed a significant phosphorylation at S39, this phosphorylation event promotes in vivo tumor metastasis and increases the ability of vimentin to induce motility and invasion." (PMID 40629272, 2025). "Increased ZEB1‐ and vimentin‐positive tumor cells with decreased membrane E‐cadherin staining were also present in these tumors, indicating pEMT to be induced in tumor cells by stromal TGF‐β1." (PMID 40644310, 2025). "Among miRNAs, hsa-miR-26a-5p expression was significantly downregulated in tumor tissue, suggesting that this low expression of hsa-miR-26a-5p resulted in the upregulation of vimentin and the downregulation of E-cadherin, which eventually promoted EMT." (PMID 40678416, 2025). "Spatial profiling via imaging mass cytometry (IMC) revealed highly proliferative Vimentin+ tumor cells within the claudin-low T12, 2151R, T11 models, and pan-CK+ tumor cells in the basal- 2336R GEMM." (PMID 40568104, 2025). "Fibronectin and vimentin showed strong expression, with an IS score of 3, in almost all of the 10 examined tumor samples." (PMID 40899568, 2025). "There were increased levels of FoxP3, vimentin, and L1CAM in PDAC cells, along with tumor-associated macrophage localization linked to tumor grades." (PMID 40699746, 2025). "N-cadherin modulates EMT-associated protein levels, such as E-cadherin and vimentin, by activating the MAPK/ERK and PI3K signaling pathways, thereby promoting both EMT and tumor metastasis." (PMID 40136409, 2025). "Immunohistochemistry revealed tumor cells positively expressed vimentin, Cluster of Differentiation 34 (CD34), cytokeratin (CK), and CD56, while they negatively expressed insulinoma-associated protein 1 (INSM1), S100, CD68, and so on." (PMID 41244767, 2025).
tumor (continued). "Tumor cells undergoing epithelial–mesenchymal transition (EMT) induce vimentin expression, making their cell division more vulnerable to changes in cell shape." (PMID 40795355, 2025). "GFAP and vimentin are often expressed in DMGs, reinforcing their astrocytic lineage, while the Ki-67 proliferation index is typically high, indicating rapid tumor growth." (PMID 40937216, 2025). "In SCLC tumors, CD70 exhibited a diffuse signal with lower expression in vimentin-positive tumor cell clusters but was present in vimentin-positive CAFs in the stroma." (PMID 40205178, 2025). "By contrast, M-tumours were abundantly VIM+ (92%) relative to E-cad+ (1.36%) or E-cad + /VIM+ (2.80%) areas." (PMID 40764669, 2025). "Immunostaining showed that CXCL5 was preferentially expressed in the CAF-rich stromal compartment of the tumor, with vimentin displaying an overlapping pattern of expression with the stroma." (PMID 41392310, 2025). "CCL26high OSCC had a characteristic of tumor invasive phenotype with upregulated CLDN8/20 and reduced keratin KRT36, which was significantly associated with EMT markers (CDH1, CDH2, VIM, SNAI2)." (PMID 39931245, 2025). "Intriguingly, this analysis also revealed enrichment in high‐Cu zones for multiple known tumor metastatic markers, including LOX (copper‐dependent enzymes as well as a tumor migration marker), vimentin, and collagen I." (PMID 40270472, 2025). "In our case, we analyzed the expression of E-cadherin and vimentin in the primary tumor as markers of the epithelial–mesenchymal transition (EMT)." (PMID 40648806, 2025). "Vimentin and N-cadherin, as well as Twist reduction, have been identified as useful biomarkers of tumor response to FDLT stimulation." (PMID 41373888, 2025). "FOXK1 is involved in decreasing the epithelial marker E-cadherin and increasing mesenchymal markers such as vimentin, thereby, aiding tumor cell invasion in GC." (PMID 39981141, 2025). "Immunohistochemistry supports the diagnosis: tumor cells are vimentin-positive, show focal/patchy SMA reactivity, and are generally negative for desmin, cytokeratins, and S-100." (PMID 41227209, 2025). "Both double and triple combinations decreased proliferative tumor cells (Ki67+, Vimentin+ and CD44+) and TAMs (F4/80+) compared to single agent treatments." (PMID 40568104, 2025). "Histopathological examination revealed UESL (7.5 cm tumor; IHC: Vimentin+, CD10+, CD56+, Ki-67 80 %)." (PMID 41332073, 2025). "Consistent with our in vitro findings, IHC staining of HRH1, ADAM9, and vimentin in tumor tissues from SAS-shHRH1-injected mice indicated downregulation of these proteins compared to control mice." (PMID 40113769, 2025). "Vimentin expression was dramatically elevated in the tumor cells of the subcutaneous tumor tissue in the Exo-Lv-miR-552-5p group, whereas E-cadherin expression decreased significantly, according to IHC analysis." (PMID 39744482, 2025). "This hallmark EMT event in early FDIM pathogenesis mirrors that of UM, where VIM upregulation correlates with increased tumour invasiveness." (PMID 40683913, 2025). "This post‐translational cascade promotes vimentin filament assembly, cytoskeletal remodeling, and tumor metastasis, with PRMT1 inhibition (MS023) reducing metastatic colonization." (PMID 40884268, 2025). "The vimentin protein expression observed in the epithelial-like models is likely due to the expression of vimentin in stromal cells present in the tumor." (PMID 40788860, 2025). "Our relevant studies demonstrated that inhibiting NLRP3 expression significantly elevated E-cadherin expression while reducing Vimentin expression in tumor cells, suggesting suppressed EMT progression." (PMID 39744485, 2025). "Vimentin plays a crucial role in tumor progression by influencing cellular plasticity, invasion, and survival under stress conditions." (PMID 40937216, 2025). "IHC depicted strongly positive neoplastic epithelium for pancytokeratin and vimentin for tumor stroma." (PMID 41451336, 2025).